NCAPH (non-SMC condensin I complex subunit H)
Diseases named in the same sentence as NCAPH in open-access papers (continued):
Sharing a sentence is not in itself a finding about the gene and the disease.
cervical cancer (continued). "The tight correlation between NCAPH and EMT was further confirmed in the xenograft tumor model suggesting NCAPH may promote EMT in cervical cancer cells." (PMID 33311486, 2020). "In vivo, NCAPH expression in cervical cancer tissues was significantly higher than which in normal cervix and high-grade squamous intraepithelial lesion (HSIL) tissues, and its expression was significantly correlated with tumor size, depth of invasion and lymph node metastasis." (PMID 33311486, 2020). "This suggests that NCAPH promotes the epithelial mesenchymal transition in cervical cancer cells." (PMID 33311486, 2020). "These factors imply that NCAPH could have an important role in promoting the progression of cervical cancer." (PMID 33311486, 2020). "Therefore, NCAPH might be an essential oncogene not limited to cervical cancer more widely involved in the development and progression of various malignancies." (PMID 33311486, 2020). "Consistently, overexpression of NCAPH improved the colony formation ability of cervical cancer cells, while the addition of RAPA significantly reduced the effects induced by overexpression of NCAPH." (PMID 39103348, 2024). "To further clarify the specific site at which NCAPH is modified by TRIM21, we added a specific site, the ubiquitin chain, to cells cocultured with cervical cancer cells." (PMID 39103348, 2024). "NCAPH inhibition restrains the proliferation, colony formation, migration, invasion and EMT process of cervical cancer cells by the PI3K/AKT/SGK pathway." (PMID 36642844, 2023). "In this study, we found that reduced expression of NCAPH can inhibit the malignant growth and the epithelial–mesenchymal transition (EMT) process of cervical cancer cells in vitro, and impede the formation of tumors in nude mice." (PMID 33311486, 2020). "More importantly, we first elucidated the regulatory loop between HPV E7 and NCAPH, and revealed the regulatory role of NCAPH on the PI3K/AKT/SGK pathway in cervical cancer." (PMID 33311486, 2020). "Our data demonstrated a novel molecular pathway in cervical cancer, that is, TRIM21 degrades NCAPH through K-11 ubiquitination, thus inhibiting the activation of the downstream AKT/mTOR pathway, promoting autophagosome formation and inhibiting cell proliferation." (PMID 39103348, 2024). "Furthermore, TRIM21 inhibited cell proliferation by hindering NCAPH-mediated activation of the AKT/mTOR pathway and autophagosome formation in cervical cancer." (PMID 39103348, 2024). "Furthermore, TRIM21 promoted autophagosome formation and reduced cell proliferation by inhibiting NCAPH expression and the downstream AKT/mTOR pathway in cervical cancer cells." (PMID 39103348, 2024). "Furthermore, interference with NCAPH significantly increased the spot ratio of mRFP to GFP, indicating that treatment promoted the autophagic process in cervical cancer cells." (PMID 39103348, 2024). "The low rate of genetic alteration indicates that the over-expression of NCAPH in cervical cancer is not mainly induced by NCAPH genetic changes." (PMID 33311486, 2020). "Similarly, the overexpression of NCAPH in cervical cancer cells induced severe cell death (data not shown)." (PMID 33311486, 2020).
colon cancer (8 papers, 2017 to 2024). "The overexpression of NCAPH is implicated in improved colon cancer prognosis, whereas the high expression of NCAPH is correlated with poor prostate cancer prognosis." (PMID 31892156, 2019). "Notably, NCAPH depletion is associated with inhibition of proliferation, migration and xenograft tumour formation in colon cancer cell lines." (PMID 38344872, 2024). "The upregulation of NCAPH is associated with poor prognosis in patients with colon cancer." (PMID 31523845, 2019). "A recent study showed that NCAPH is upregulated in colon cancer and associated with poor prognosis." (PMID 31523845, 2019). "Owing to the higher expression of NCAPH in colonic cancerous cell lines, we speculated that NCAPH might play important roles and be frequently mutated in human colon cancers." (PMID 28300828, 2017). "NCAPH is increased in colon cancerous tissues and NCAPH depletion inhibits colon cancer growth, and migration, and induces cell apoptosis and cell cycle arrest." (PMID 36642844, 2023). "In colon cancer, NCAPH promotes tumor formation, cell proliferation, and apoptosis and G2/M arrest inhibition." (PMID 31892156, 2019). "However, our results indicate that patients with NCAPH high expression in colon tumor tissues might be associated with better prognosis, which could be explained by NCAPH sensitizing highly proliferating colon cancerous cells responding to chemo- and/or radio-therapies." (PMID 28300828, 2017). "We identified NCAPH high expression in colon tumor tissues as a biomarker that has been found in a majority of CC." (PMID 28300828, 2017). "To examine the exact functional roles of NCAPH in colon cancers, we first analyzed the relative mRNA and protein expressions of NCAPH in normal human colonic epithelial cell and colorectal cancerous cell lines (LoVo, SW480, SW620 and HCT116)." (PMID 28300828, 2017). "Moreover, it has been reported that the high expression of NCAPH in tumor tissues of patients with colon cancer had a significantly better prognosis and survival rate than patients with low expression." (PMID 32196072, 2020). "To verify whether NCAPH is important for colonic cancer cell growth in vivo, we performed a tumorigenesis assay in nude mice." (PMID 28300828, 2017).
prostate carcinoma (8 papers, 2019 to 2025). A carcinoma that arises from epithelial cells of the prostate gland. "The present study revealed the oncogenic role and regulatory mechanism of NCAPH in the prostate cancer cells." (PMID 39991770, 2025). "We further examined NCAPH expression in 24 pairs of clinical prostate cancer tissues (tumor tissues, n=24; adjacent tissues, n=24) using real-time quantitative PCR (RT-qPCR) and immunohistochemistry (IHC)." (PMID 39991770, 2025). "Our findings revealed that silencing the NCAPH gene effectively suppressed proliferation, reduced cell cycle progression in prostate cancer cells by directly inhibiting the PI3K/AKT/mTOR pathway, and decreased the expression of the transcription factor E2F1." (PMID 39991770, 2025). "Current researches showed that NCAPH up-regulated predicts a poor prognosis of prostate cancer patients and NCAPG promotes the progression of LUAD." (PMID 38172945, 2024). "For instances, NCAPH is significantly upregulated in prostate cancer, and NCAPH silencing suppresses cell proliferation and metastasis." (PMID 34399777, 2021). "Although NCAPH expression was also an independent poor prognosticator for patients with OSCC, other reports indicated that NCAPH overexpression is strongly correlated with worse prognoses in prostate cancer." (PMID 31892156, 2019). "However, the exact mechanisms by which NCAPH promotes malignancy in prostate cancer cells remain unclear." (PMID 39991770, 2025).
colorectal cancer (7 papers, 2017 to 2025). A primary or metastatic malignant neoplasm that affects the colon or rectum. "NCAPH was proved highly expressed in colorectal cancer cell lines comparing with normal human colonic epithelial cells, and many NCAPH mutations in colorectal cancer patients were identified, but it was not detailed in EC." (PMID 31139013, 2019). "Many NCAPH mutations include missense and frameshift are identified in colorectal cancer patients." (PMID 34557090, 2021). "In colorectal cancer, depletion of NCAPH significantly inhibits the tumor growth and migration and induces apoptosis as well as cell cycle arrest." (PMID 38587786, 2025). "In fact, in colorectal cancer cells, the knockdown of NCAPH induced cell cycle arrest at the G2/M phase." (PMID 34768935, 2021). "We provided evidences showing that NCAPH is highly expressed in colorectal cancer cell lines comparing with normal human colonic epithelial cells, and identified many NCAPH mutations in CC patients." (PMID 28300828, 2017). "Finally, NCAPH is overexpressed in colorectal cancer cell lines comparing with normal human colonic epithelial cells." (PMID 34557090, 2021).
lung adenocarcinoma (6 papers, 2022 to 2025). A carcinoma that arises from the lung and is characterized by the presence of malignant glandular epithelial cells. "NCAPH was associated with the development and progression of lung adenocarcinoma and represented a potential therapeutic target in lung adenocarcinoma." (PMID 38755247, 2024). "In this study, we found that the expression of NCAPH was up-regulated in lung adenocarcinoma compared to standard control based on the TCGA and GEO database." (PMID 38755247, 2024). "In vitro and in vivo, miR-1976 impairs cell growth and metastasis and promotes apoptosis of lung adenocarcinoma by targeting NCAPH/ NF-κB axis." (PMID 38755247, 2024). "In conclusion, this study demonstrates that miR-1976, targeting NCAPH, can operate as a tumor suppressor and decrease the malignant phenotypes of lung adenocarcinoma." (PMID 38755247, 2024). "Besides, NCAPH is positively correlated with the level of acquired immune cells (Th2 cells) in lung adenocarcinoma." (PMID 38587786, 2025). "However, how NCAPH is involved in the progression of lung adenocarcinoma remains unclear." (PMID 38755247, 2024). "However, we found that miR-1976, but not miR-133b, targeting NCAPH, was involved in lung adenocarcinoma's growth, metastasis, and apoptosis." (PMID 38755247, 2024).
lung cancer (5 papers, 2017 to 2024). A malignant neoplasm involving the lung. "There are a lot of studies in tumors that might play a crucial role in the occurrence of development and process of HCC47 and may also be an important contributor to the development of nonsmall cell lung cancer, that is, NCAPH can promote the proliferation of cancer cells." (PMID 39346787, 2024). "Moreover, lung cancer patients' survival was strongly correlated with the expression of NCAPH." (PMID 38755247, 2024). "We found that E2F1 regulated genes enriched in ‘cell division’ across all three subtypes, with three target genes in the GO term commonly regulated in lung cancers: CCNF (cyclin F), NCAPH (Non-SMC Condensin I Complex Subunit H), SPAG5 (Sperm Associated Antigen 5)." (PMID 29866045, 2018).
endometrial cancer (4 papers, 2021 to 2025). Primary or metastatic malignant neoplasm involving the endometrium (mucous membrane that lines the endometrial cavity). "The results revealed that missense mutations, amplification, and deep deletion were the predominant forms of NCAPH mutations, with endometrial cancer, melanoma, and non-small cell lung cancer being the most frequently mutated cancer types." (PMID 41210692, 2025). "Compelling evidence indicates that NCAPH functions as an oncogene in endometrial cancer and breast cancer, and its highly expression represents a poor prognosis." (PMID 34399777, 2021). "In endometrial cancer, significantly upregulated NCAPH expression is observed in clinical tissues when compared to the normal tissues, which is associated with poor clinicopathologic characteristics." (PMID 34399777, 2021).
hepatocellular carcinoma (4 papers, 2019 to 2025). A malignant tumor that arises from hepatocytes. "In hepatocellular carcinoma, elevated NCAPH expression levels have been observed compared to normal tissue, promoting tumor cell proliferation, migration and invasion." (PMID 41210692, 2025). "However, the relationship between NCAPH and hepatocellular carcinoma (HCC) remains unclear." (PMID 31523845, 2019).
non-small cell lung carcinoma (4 papers, 2021 to 2025). A group of at least three distinct histological types of lung cancer, including non-small cell squamous cell carcinoma, adenocarcinoma, and large cell carcinoma. "NCAPH inhibits phosphorylation of β-catenin by forming a complex with β-catenin and activating Wnt signaling to promote the formation of non-small cell lung cancer." (PMID 37184686, 2023). "Another study has determined that aberrantly high NCAPH overexpression is required for proliferation, migration, and invasion of non-small cell lung cancer." (PMID 34399777, 2021).
ovarian carcinoma (4 papers, 2013 to 2021). A malignant neoplasm originating from the surface ovarian epithelium. "NCAPH overexpression is associated with resistance to carboplatin and radiation in ovarian cancer and colorectal cancer (CRC), respectively." (PMID 31892156, 2019). "This study was aimed to explore the role of non-structure maintenance of chromosomes condensin I complex subunit H (NCAPH) in the progression of ovarian cancer (OC) and the transcription regulatory effects of GATA binding protein 3 (GATA3) on this gene." (PMID 34399777, 2021). "Considering that NCAPH expression is related to carboplatin resistance in ovarian cancer cells, we analyzed the effect of NCAPH on OSCC cell tolerance to platinum anticancer drugs by using a multidrug-resistance (MDR) assay kit." (PMID 31892156, 2019).
bladder cancer (3 papers, 2024 to 2025). "NCAPH promotes cell proliferation and apoptosis of bladder cancer cells through the MEK/ERK signaling pathway." (PMID 39346787, 2024). "Furthermore, heightened expression of NCAPH has been observed in bladder cancer, where it facilitates the proliferation of bladder cancer cells and suppresses their programmed cell death by activating the MEK/ERK pathway, consequently impacting the progression of bladder cancer." (PMID 41210692, 2025).
melanoma (3 papers, 2007 to 2025). A malignant, usually aggressive tumor composed of atypical, neoplastic melanocytes. "For example, NCAPH (i.e. hCAP-H) is upregulated in melanomas." (PMID 29467813, 2018).
pancreatic cancer (3 papers, 2019 to 2025). "In pancreatic cancer (PC) cell lines, the down-regulated NCAPH inhibited PC cell proliferation and colony formation." (PMID 38755247, 2024). "However, the mechanisms through which NCAPH affects pancreatic cancer (PC) and its molecular function remain unclear." (PMID 31784646, 2019).
breast tumors (2 papers, 2023 to 2024). "Thus, high NCAPH expression in luminal A breast tumours is associated with a poorer prognosis and therapy response, indicating its potential as an identifier for high‐risk luminal A tumours." (PMID 38344872, 2024). "Transgenic mice overexpressing NCAPH developed breast tumours with extended latency, and in Mouse Mammary Tumor Virus (MMTV)‐NCAPHErbB2 double‐transgenic mice, luminal tumours showed increased aggressiveness." (PMID 38344872, 2024). "MMTV‐NCAPHErbB2 double‐transgenic mice overexpressing NCAPH generated more aggressive breast tumours, and in a cohort of genetically heterogeneous transgenic mice generated by backcrossing, these tumours had a worse outcome and a poor response to chemotherapy." (PMID 38344872, 2024). "Together, these results indicate that NCAPH is oncogenic in breast tumours." (PMID 38344872, 2024). "Indeed, the overexpression of NCAPH, regulated by the MMTV promoter in this transgenic line, resulted in breast tumour development with reduced latency post‐pregnancy, suggesting a dose‐dependent effect." (PMID 38344872, 2024). "Indeed, transgenic mice overexpressing NCAPH generated breast tumors with long latency, and in MMTV-NCAPH/ErbB2+ double-transgenic mice, the luminal tumors formed were more aggressive." (PMID 37886490, 2023).
clear cell renal carcinoma (2 papers, 2023 to 2025). A malignant epithelial neoplasm of the kidney characterized by the presence of lipid-containing clear cells within a vascular network. "This suggests that NCAPH could potentially serve as a therapeutic target for reversing immune tolerance in patients with clear cell renal cancer." (PMID 41210692, 2025). "The elevated NCAPH proteins then enhance the stability of β‐catenin and activate β‐catenin‐related signalling pathway, which further promotes aerobic glycolysis and immune escape of clear cell renal cell carcinoma." (PMID 36642844, 2023). "However, the function and regulatory mechanism of NCAPH in clear cell renal cell carcinoma (ccRCC) remain unknown." (PMID 36642844, 2023).
glioblastoma (2 papers, 2025). The most malignant astrocytic tumor (WHO grade IV). "Before that, to explore the potential function of NCAPH in glioma more comprehensively, low-grade glioma (LGG) and glioblastoma multiforme (GBM) were combined into glioma group (GBMLGG) for analysis." (PMID 38587786, 2025).